OPA1 (OPA1 mitochondrial dynamin like GTPase)
Diseases named in the same sentence as OPA1 in open-access papers (continued):
Sharing a sentence is not in itself a finding about the gene and the disease.
dementia (9 papers, 2017 to 2025). Loss of intellectual abilities interfering with an individual's social and occupational functions. "In the context of neurodegeneration and dementia, OPA1 mutations may impair mitochondrial fusion, cristae integrity, and energy metabolism, contributing to synaptic dysfunction and neuronal loss." (PMID 40354372, 2025). "Therefore, the amplification index of DRP1 and OPA1 in peripheral blood were associated with the occurrence of diabetic neurocognitive impairment and dementia, and had a certain predictive effect on their occurrence." (PMID 37563583, 2023). "DNA amplification multiples of DRP1 and OPA1 are associated with the risk of dementia in elderly patients and may serve as potential biomarkers." (PMID 37563583, 2023). "The HbA1c and DRP1 (2− K) levels were significantly higher, while LDL and OPA1 (2− K) levels were significantly lower in the dementia group compared with the normal and MCI groups." (PMID 37563583, 2023). "The amplification of OPA1 had a better accuracy for the diagnosis of dementia (AUC = 0.9289, P < 0.0001)." (PMID 37563583, 2023). "We further evaluated the correlation between DRP1/OPA1 gene amplification and AD8/MoCA score as a risk assessment criterion for dementia." (PMID 37563583, 2023). "DRP1(2− K) and OPA1(2− K) significantly increased and decreased in dementia and MCI groups compared with the normal group (P ≤ 0.001)." (PMID 37563583, 2023). "Analysis of ROCs showed that the DNA amplification factor of OPA1 had a higher predictive value for dementia (P < 0.0001), and that it had a higher predictive value when used in combination with DRP1." (PMID 37563583, 2023). "Experimental evidence links OPA1 to the pathogenesis of Parkinsonian syndrome and dementia, while OXCT1 plays a central role in extrahepatic ketone body catabolism." (PMID 34683848, 2021). "ROC analysis showed that the combined predictive value of DRP1 and OPA1 was higher than that of the individual predictive values in both MCI and dementia groups." (PMID 37563583, 2023). "The multiples of DRP1 and OPA1 amplification were positively correlated with AD8 and MoCA scores, which were evaluation tools for screening cognitive impairment and dementia." (PMID 37563583, 2023). "High DRP1 DNA expression and low OPA1 DNA expression have predictive value for cognitive deficits and may be promising biomarkers for MCI and dementia." (PMID 37563583, 2023).
Alzheimer disease (8 papers, 2019 to 2025). A progressive, neurodegenerative disease characterized by loss of function and death of nerve cells in several areas of the brain leading to loss of cognitive function such as memory and language. "Diminished OPA1 expression and impaired mitochondrial morphology in microglia during Alzheimer’s disease." (PMID 40354372, 2025). "Our findings reveal a previously unrecognized function of OPA1 in Aβ clearance, providing novel insights into potential therapeutic avenues for Alzheimer’s disease." (PMID 40354372, 2025). "For instance, in neurons from the hippocampus of Alzheimer’s disease patients, reduced expression of Opa1, Mfn1/2, and Drp1, along with increased Fis1 levels, has been observed." (PMID 41465333, 2025). "Pretreatment with SS-31 also reversed alterations in the expression of the mitochondrial proteins dynamin-related protein (DRP) 1, FIS1, mitofusin (MFN) 1, MFN2, and OPA1 in Alzheimer disease." (PMID 34221235, 2021). "Mitochondrial fusion protein OPA1 is depleted in dendrites in hippocampal neurons in Alzheimer’s disease." (PMID 33094281, 2020). "Moreover, the levels of proteins governing mitochondrial dynamics, which include OPA1, have been found to be significantly altered in Alzheimer Disease (AD) mice and patients." (PMID 33927681, 2021). "Supportively, a previous study showed that 12-week treadmill training increased the levels of fusion proteins (OPA-1 and MNF-2) in the hippocampus of an Alzheimer’s disease mouse model." (PMID 34440215, 2021).
Sepsis (8 papers, 2019 to 2025). Sepsis is defined as life-threatening organ dysfunction caused by a dysregulated host response to infection. "In contrast, NR4A1 inhibited MFN1, MFN2, and OPA1 expression, worsening lung injury caused by sepsis." (PMID 40177356, 2025). "In the Severe vs. Control group, the genes associated with ER stress, including CLU (p = 0.01), BCL2L1 (p = 0.015), USP14 (p = 0.046), BFAR (p = 0.004), and OPA1 (p = 0.012), demonstrated a significant positive correlation with sepsis score." (PMID 40867920, 2025). "Opa1 expression, contributing to mitochondrial fusion processes, was upregulated with sepsis (P < 0.01 vs. healthy control mice), whereas the expression of Fis1 remained unaltered (P = 0.2)." (PMID 41385533, 2025). "Our results showed that the expression of Drp1 and Fis1 was increased, while OPA1, Mfn1 and Mfn2 were decreased in the intestinal epithelium during sepsis, indicating increased mitochondrial fission and insufficient mitochondrial fusion." (PMID 36581806, 2022). "Studies on sepsis-induced lung injury, caused by cecal ligation puncture or lipopolysaccharide (LPS), have shown decreased expression levels of mitochondrial fusion proteins MFN2 and OPA1 in lung tissue, alveolar epithelial cells, and macrophages." (PMID 40177356, 2025). "The levels of CLU, BCL2L1, USP14, PTPN1, OPA1, and CREB3 were elevated during sepsis and demonstrated a positive correlation with sepsis score." (PMID 40867920, 2025). "In alveolar macrophages of sepsis-induced ALI, there was a noted decrease in SIRT3 protein expression alongside an increase in OPA1 acetylation." (PMID 40867920, 2025). "Imbalanced mitochondrial dynamics stimulate pro-inflammatory polarization of alveolar macrophages in sepsis-induced ALI, while the deacetylation of optic atrophy protein 1 (OPA1) facilitated by SIRT3 enhances MD equilibrium, thus alleviating lung injury." (PMID 40867920, 2025). "This study presents findings on several genes linked to ER stress, including CLU, BCL2L1, USP14, BFAR, and OPA1, which showed a positive correlation with sepsis score and a negative correlation with the combined activities of antioxidant enzymes." (PMID 40867920, 2025). "While levels of mitochondrial fusion-related genes Opa1 and Mfn2 were not different between groups, levels of mitochondrial fission-related genes, Fis1 and Dnm1l, were increased in Sepsis by 16% (p = 0.0197) and 42.1% (p = 0.0416), respectively." (PMID 41315622, 2025). "Similarly, our results showed that the mitochondrial fusion-fission balance shifts toward mitochondrial fission during sepsis, as reflected by a decrease in MFN2 and OPA1, an increase in Drp1 translocation and Drp1 phosphorylation, and a decrease in mitochondrial size and elongated mitochondria." (PMID 31263382, 2019).
Charcot-Marie-Tooth disease (7 papers, 2013 to 2025). An inherited degenerative disorder involving the peripheral nerves. "Mice deficient in Mfn1, Mfn2, and OPA1 are all embryonic lethal and in humans, mutations in OPA1 are linked to hereditary blindness, and Mfn2 mutations are known to cause Charcot-Marie-Tooth disease." (PMID 29062571, 2017). "Knockout mice of Mfn1, Mfn2, and OPA1 are all embryonic lethal and mutations in OPA1 in humans are associated with hereditary blindness, while Mfn2 mutations are the cause of Charcot-Marie-Tooth disease." (PMID 28097021, 2016).
Charcot-Marie-Tooth disease type 2A (7 papers, 2011 to 2025). "Mutations in MFN2 and OPA1 are associated with human neuropathies, such as Charcot-Marie-Tooth disease type 2A (CMT2A) and dominant optic atrophy (DOA), respectively." (PMID 24957874, 2011).
diabetic cardiomyopathy (7 papers, 2017 to 2025). Diabetic cardiomyopathy is a disorder of the heart muscle in people with diabetes. "Downregulation of Mfn2 exacerbates diabetic cardiomyopathy, and recent studies have shown that brain natriuretic peptide (BNP) protects against diabetic cardiomyopathy by promoting OPA1-mediated mitochondrial fusion through activation of the PKG-STAT3 pathway." (PMID 41000071, 2025). "To further underscore the beneficial role of OPA1 in diabetic cardiomyopathy, we investigated the effects of OPA1 upregulation on apoptosis and ROS in AC16 cells." (PMID 38777955, 2024). "Similarly, the mitochondrial fusion enhancing substance M1 can effectively restore mitochondrial balance and improve diabetic cardiomyopathy in an OPA1-dependent manner." (PMID 34660720, 2021). "In a consistent way, overexpression of OPA1 may help ameliorate the cardiac dysfunction in diabetes cardiomyopathy." (PMID 28928601, 2017). "In terms of diabetic cardiomyopathy, punicalagin and paeonol are potent mitochondrial fusion promoters by regulating STAT3 and Opa1 levels." (PMID 39571159, 2024).
neuropathy (7 papers, 2014 to 2023). A disorder affecting the nervous system that manifests with pain, tingling, numbness, and/or muscle weakness. "Opa1 dysfunction have been known resulted in RGC neuropathy, increasing the susceptibility of RGCs to apoptosis and vulnerability to oxidative stress." (PMID 34621753, 2021). "In general, OPA1 protein reduction affected neuronal function mainly by affecting presynaptic proteins, postsynaptic proteins, and synaptic transmission, and then caused neuropathy." (PMID 37563583, 2023). "In addition, Opa1 is the most widely employed gene for studying the mitochondrial dynamics with neuropathy and has well-known roles in both mitochondrial fusion and crista remodeling." (PMID 33802485, 2021).
ovarian carcinoma (7 papers, 2018 to 2025). A malignant neoplasm originating from the surface ovarian epithelium. "Further supporting the concept of differential drug sensitivity, the study also showed that OPA1 or DNML1 deletion in the MCAS ovarian carcinoma cell line causes sensitization to BCL-2 and MCL-1 inhibitors but not to apoptosis-inducing etoposide." (PMID 41146909, 2025). "In fact, increased levels of OPA1 protein associated with the increase in mitochondrial length, and thus fusion process, have been reported in ovarian cancer tissue." (PMID 36674740, 2023). "OPA1 processing in ovarian cancer cells is also mediated by PHB1." (PMID 36674740, 2023). "Furthermore, studies conducted on ovarian cancer cell cultures have shown that chemoresistance to some drugs is partly due to a deregulation of OPA1 processing." (PMID 36674740, 2023). "Studies in ovarian cancer cell cultures showed that the chemoresistance to some drugs such as cisplatin, the first platinum-based complex to treat patients with OC, is partly due to a deregulation of OPA1 processing, which results in an increase of mitochondrial fusion and decreased apoptosis." (PMID 36674740, 2023). "The high expression of OPA1 showed statistically significant with P < 0.05 in both breast and gastric cancer (P = 1.6e-06, respectively); while SENP5 was associated with RFS in the other two cancer types – ovarian cancer (P = 0.011) and gastric cancer (P = 1.1e-05)." (PMID 29459674, 2018). "Mechanistically, in ovarian cancer, OMA1 cleaved optic atrophy 1 (OPA1), leading to mitochondrial inner membrane cristae remodeling." (PMID 35163244, 2022). "To examine the role of mitochondrial dynamics in DDP resistance in ovarian cancer cells, we first examined the expression of mitochondrial dynamics-related proteins including MFN1, MFN2, DRP1, and OPA1 in SKOV3 and SKOV3/DDP cells." (PMID 35003356, 2021). "We highlight, in the heterogeneity of ovarian cancer, a characteristic “mitochondrial signature”, characterized by increased mitochondrial biogenesis and altered mitochondrial structure that could result from the cooperation of cAMP pathway and the SIRT3, OPA1, and PHB2 proteins." (PMID 31547300, 2019).
atherosclerosis (6 papers, 2020 to 2025). A disease characterized by the build-up of fatty material and calcium deposition in the arterial wall resulting in partial or complete occlusion of the arterial lumen. "In agreement, Opa1 expression was decreased in the lower curvature of the mouse aortic cross which is an atheroprone zone compared to the greater curvature which is less susceptible to atherosclerosis." (PMID 35739974, 2022). "MT acted either through the SIRT3-FOXO3 (forkhead box O3)-PRKN signaling cascade in a murine model of atherosclerosis or through the mitochondrial dynamin-like GTPase (OPA1)/AMPK axis in an ischemia-reperfusion model." (PMID 37107334, 2023). "In summary, our data provided evidence that Punisher exerts an antiapoptotic and antimitochondrial fission function in VSMCs by targeting miR-664a-5p and its downstream target OPA1 and therefore alleviating the development of atherosclerosis." (PMID 35663194, 2022). "This was confirmed by our results showing that both the mouse model of ADOA (Opa1+/− mice) and mice lacking Opa1 in ECs were more susceptible to atherosclerosis when fed a high-fat diet." (PMID 35739974, 2022). "Our data provides the significant relationship among OPA1, mitochondrial homeostasis, VSMC apoptosis, and atherosclerosis." (PMID 35663194, 2022). "The present study demonstrates that the mitochondrial fusion protein Opa1 is involved in ECs’ response to acute changes in flow (FMD), with a protective effect against atherosclerosis." (PMID 35739974, 2022). "This suggested that the protective effect of CoQ10 against atherosclerosis might be related to the AMPK-YAP-OPA1 pathway, and AMPK negatively regulated YAP and promoted the expression of OPA1, thus inhibiting oxidative stress and promoting energy metabolism." (PMID 32792941, 2020).
hepatocellular carcinoma (6 papers, 2017 to 2023). A malignant tumor that arises from hepatocytes. "The knockdown of Opa1 inhibited the fusion process in hepatocellular carcinoma cell lines and cholangiocarcinoma tumor organoids." (PMID 37900170, 2023). "In hepatocellular carcinoma, cell apoptosis was directly induced via targeting Opa1 to trigger mitochondrial injury." (PMID 29050288, 2017). "In hepatocellular carcinoma, the down-regulation of Opa1 expression was also found to be involved in apoptosis." (PMID 29050288, 2017). "Taking LIHC as an example, some researchers found that OPA1 downregulation can enhance the sensitivity of hepatocellular carcinoma to chemotherapy drug sorafenib, which indicates that low expression of OPA1 is associated with a better prognosis of hepatocellular carcinoma." (PMID 37980164, 2023). "Furthermore, increases in MFNs and OPA1 expression have been reported for replicative senescence of human hepatoma cell and mink lung epithelial cells." (PMID 28758339, 2017). "Finally, we show that mRNA levels of OPA1 isoforms containing Exon4b are specifically downregulated in hepatocellular carcinoma (HCC), leading to a reduction in Δψm." (PMID 32373606, 2020).
Hypertension (6 papers, 2014 to 2025). The presence of chronic increased pressure in the systemic arterial system. "Polymorphisms in mitochondrial dynamin like GTPase (OPA1) were reported to have an age-dependent association with blood pressure and hypertension in a Korean population." (PMID 28270201, 2017). "From a therapeutic standpoint, stabilizing cristae structure (perhaps by preventing MICOS loss or enhancing OPA1 activity) might preserve mitochondrial function in hypertension." (PMID 41007357, 2025). "We have previously shown that Opa1+/− mice are more susceptible to arterial hypertension and that FMD is selectively reduced in a mouse model with Opa1 deficiency in ECs only (EC‐Opa1 mice)." (PMID 40616272, 2025). "On the fusion side, hypertension may reduce the expression of mitofusins and OPA1, or functionally impair them via post-translational modifications." (PMID 41007357, 2025). "Furthermore, reduced Opa1 expression enhanced angiotensin II‐induced hypertension in Opa1+/− mice." (PMID 40616272, 2025). "This study suggests that acacetin protected against endothelial dysfunction in hypertension by activating the AKT/eNOS pathway and modulating mitochondrial function by targeting mPTP and DRP1/OPA1-dependent dynamics." (PMID 36232649, 2022).
Wolfram syndrome (6 papers, 2014 to 2025). Wolfram syndrome (WS) also known as DIDMOAD, is a neurodegenerative disorder characterized by type I diabetes mellitus (DM), diabetes insipidus (DI), sensorineural deafness (D), bilateral optical atrophy (OA) and neurological signs. "This differential diagnosis includes e.g. OPA3/Type III methylglutaconic aciduria (MIM 606580), OPA1 (MIM 605290) or Wolfram Syndrome (MIM 606201)." (PMID 24528855, 2014).
acute kidney injury (5 papers, 2022 to 2026). Sudden and sustained deterioration of the kidney function characterized by decreased glomerular filtration rate, increased serum creatinine or oliguria. "Inhibits OPA1 hydrolysis, mitochondrial division, oxidative stress and apoptosis and shows new therapeutic potential in the treatment of acute kidney injury." (PMID 35566359, 2022). "On the other hand, research on matrine (MAT), which plays multiple pharmacological roles, found that it protected against cisplatin-induced acute kidney injury (AKI) by antioxidative stress and anti-inflammation actions via the SIRT3/OPA1 pathway." (PMID 39765772, 2024). "Moreover, in a study was related to ischemia/reperfusion-induced acute kidney injury, Hyp pretreatment reduced TUNEL-positive cells and the level of cleaved Caspase-3, attenuated the decreased expression of Opa1, inhibited mitochondrial fission." (PMID 40978492, 2025).
acute myeloid leukemia (5 papers, 2022 to 2025). Acute myeloid leukemia (AML) is a group of neoplasms arising from precursor cells committed to the myeloid cell-line differentiation. "In addition, it has also been reported that OPA1-mediated suppression of cytochrome c release is linked to venetoclax resistance in acute myeloid leukemia (AML), which is an example of acquired drug resistance." (PMID 41008599, 2025). "For instance, upregulated OPA1 confers resistance to cytochrome c release upon prolonged venetoclax treatment in acute myeloid leukemia (AML) cells." (PMID 35851420, 2022). "Finally, in acute myeloid leukemias (AML) resistant to the Bcl-2 antagonist venetoclax, OPA1 inhibition restores sensitivity to venetoclax." (PMID 35279198, 2022).
Cognitive impairment (5 papers, 2020 to 2025). Abnormal cognition is characterized by deficits in thinking, reasoning, or remembering. "This study aimed to investigate the relationship between DRP1 and OPA1 and the risk of cognitive impairment." (PMID 37563583, 2023). "Hence, we associate the cognitive impairments in Opa1+/− mice evidenced here in object location and metric-spatial pattern separation tasks with defects in these maturing neurons." (PMID 37863658, 2023). "Increasing evidence has shown that CHCHD2 and CHCHD10 are associated with cognitive disorders and motor neuron diseases through their interactions with proteins such as OMA-1, OPA-1, TDP43, PINK, and p62." (PMID 36061599, 2022). "In our study, we also observed reduced OPA1 expression in AD patients and APP/PS1 mice and found that OPA1 activation could improve cognitive impairment in AD mice." (PMID 40354372, 2025). "In Opa1+/− mice, the reduced number of new neurons and their limited connectivity within the hippocampal network may contribute to cognitive impairments." (PMID 37863658, 2023). "As Opa1+/− mice are visually compromised, we had a limited choice of suitable cognitive tests and were not able to determine the exact phenotype of cognitive impairment." (PMID 33094281, 2020). "The review highlights the different roles played by CHCHD2 and/or CHCHD10 binding to various target proteins (such as OPA-1, OMA-1, PINK, and TDP43) and reveals their non-negligible effects in cognitive impairments and motor neuron diseases." (PMID 36061599, 2022).